PIN1 (peptidylprolyl cis/trans isomerase, NIMA-interacting 1)
Diseases named in the same sentence as PIN1 in open-access papers (continued):
Sharing a sentence is not in itself a finding about the gene and the disease.
cancer (continued). "Multiple signaling pathways are involved in cancer cell proliferation and downregulation of apoptosis, including PIN1-Hippo pathway, but its role in OS progression remains unclear." (PMID 37006999, 2023). "Prolyl isomerase 1 (Pin1) is a peptidyl-prolyl cis/trans isomerase that regulates the biological functions of a variety of proteins through conformational changes and has a key role in Alzheimer’s disease and several cancers." (PMID 36770689, 2023). "Targeting PIN1, lying at the heart of signalling pathways important for cancer initiation and development may have value." (PMID 36707636, 2023). "Nevertheless, the role of Pin1 in cancer metastasis, especially the inhibitory effect of Pin1 inhibitors on cancer metastasis, is unknown." (PMID 36915713, 2023). "Accumulating evidence indicates that Pin1 plays a key role in various cancers." (PMID 36829834, 2023). "To this end, we used Sulfopin, a recently identified covalent Pin1-specific inhibitor that targets the functionally critically Cys113 and the ATO-binding pocket in the Pin1 catalytic active site and effectively inhibits Pin1 function in cancer in vitro and in vivo." (PMID 37669931, 2023). "PIN1 is a phosphorylation-directed proline isomerase and a master cancer signaling regulator." (PMID 36711754, 2023). "Since EGCG can bind to PIN1 and promote anticancer activities and may induce cancer cell apoptosis, we examined whether EGCG-mediated inhibition of PPIases parvulins PIN1 and PIN4 affects HBV replication in HCC cell lines." (PMID 36760500, 2023). "Therefore, future research delineating Pin1’s function in different cell types and genetic background is greatly needed and would be important to determine Pin1 as a target for cancer therapy, which is also highly relevant to precision medicine." (PMID 37508437, 2023). "Furthermore, it has been demonstrated that inhibiting Pin1 increases the sensitivity of certain cancer cells to chemotherapeutic treatments." (PMID 37375103, 2023). "It has been suggested that PIN1 may serve as a unique and critical regulator connecting cancer and AD." (PMID 38250575, 2023). "Since Pin1 has been suggested as a therapeutic cancer drug target, and development of more potent and specific Pin1 inhibitors is underway, our data suggest that Pin1-targeting drugs may also be good candidate treatments for chronic HBV and HBV-associated HCC." (PMID 37404723, 2023). "Therefore, Pin1 can be used as a molecular probe to capture cancer-specific phosphoproteins responsible for the oncogenesis and sustained malignant properties of cancers." (PMID 38089883, 2023). "The PIN1 gene, which is necessary for tau phosphorylation, is also overexpressed in certain cancers, and the PARK2 gene, which is responsible for producing an E3 ubiquitin ligase, may also be a tumor suppressor." (PMID 36765585, 2023). "Pin1 played a key role in cancer metastasis and was the main target of ATRA-NPs." (PMID 36915713, 2023). "Prior findings suggest that Pin1 contributes to the pathogenesis of multiple human cancers." (PMID 38020885, 2023). "ATO together with all trans-retinoic acid (ATRA) has been shown to block several cancer-associated signaling pathways and eliminate tumor-initiating cells in TNBC by targeting peptidyl-prolyl isomerase (PIN1), an enzyme involved in various cellular processes that are aberrant in tumor cells." (PMID 38136293, 2023). "Notably, as malignant tumors often express enhanced Pin1-Hsp90α signaling pathways, this provides a potential therapeutic target for tumors." (PMID 36829834, 2023).
cancer (continued). "The unique proline isomerase Pin1 activates numerous cancer pathways, but its role in cancer metastasis and the inhibitory efficacy of Pin1 inhibitors on cancer metastasis are unknown." (PMID 36915713, 2023). "Next, we investigated the effect of PIN1 on pVHL in other types of cancers." (PMID 36813923, 2023). "In several instances, increased levels of Pin1 correlate with poor clinical outcome, indicating that Pin1 levels might have a prognostic value for cancer." (PMID 37050909, 2023). "PIN1 has been reported to promote tumor progression of various cancers." (PMID 36813923, 2023). "Pin1 regulates proliferation and migration of cancer by modulating P21 transactivation." (PMID 35461311, 2022). "However, identifying a Pin1-specific drug with good cancer therapeutic effect remains elusive, thus leading to the continued efforts in Pin1 research." (PMID 36111342, 2022). "PIN1, a multifunctional gene hypothesized to act as a “molecular timer”, is upregulated in a number of cancers and downregulated in AD." (PMID 35741059, 2022). "in their study suggested ATRA may also bind and degrade the peptidyl-prolyl cis/trans isomerase PIN1 in cancer cells." (PMID 35493504, 2022). "Thus, further research on Pin1 can provide clues for exploring the treatment of neurological diseases and cancer." (PMID 36393861, 2022). "Moreover, abnormalities in Pin1 are involved in the occurrence and progression of neurological diseases and cancer through many mechanisms." (PMID 36393861, 2022). "Compelling data suggest that Pin1 can treat human cancer and is targeted." (PMID 35450041, 2022). "Among the top 10 co-cited articles, there are many studies on Pin1 and cancer." (PMID 36393861, 2022). "Besides cancer, various studies also highlighted Pin1’s contribution to neurodegenerative diseases, such as Alzheimer’s disease (AD) and Parkinson’s disease (PD)." (PMID 36111342, 2022). "Overexpression of Pin1 has been reported in many human cancers and cancer cell lines." (PMID 35433695, 2022). "In addition, the role of Pin1 in cancer and the potential of Pin1 inhibitors to restore this balance have been discussed." (PMID 36393861, 2022). "Although chemical Pin1 inhibitors elicit potent antitumor effects against several human cancers, their inhibitory impact on the tumorigenic capacity of CD44+CD133+ tumor-initiating Caco-2 cells was unknown." (PMID 35433695, 2022). "Moreover, Pin1 is commonly overexpressed in most cancers and high levels of Pin1 expression is correlated with poor prognosis in various cancers." (PMID 33807199, 2021). "Pin1 tends to be upregulated in cancer cells and cells with active proliferation." (PMID 34535740, 2021). "Pin1 was originally identified as a regulator of mitosis and many previous studies have indicated that it drives multiple proliferation-promoting pathways in cancer development." (PMID 33807199, 2021). "In addition, emerging evidence suggests that inhibitors targeting Pin1 have significant anti-cancer effects." (PMID 33537091, 2021). "The literature proposes a correlation between PIN1 and cyclin D1, in which PIN1 increases cyclin D1 transcription directly or by Jun N terminal Kinase and/or cytokine-nuclear factor (NF)-κB pathways, resulting in increased proliferation of cancer cells." (PMID 33907248, 2021). "Pin1-promotion of proliferation via the NF-κB signaling pathway has been found in various cancers." (PMID 33807199, 2021). "Pin1 expression is higher in metastatic cancer compared with primary cancer." (PMID 33807199, 2021).
cancer (continued). "Many studies have revealed roles of Pin1 in cancers, metabolism, and Alzheimer’s disease." (PMID 34535740, 2021). "Pin1 is a critical defense against genotoxic insult-induced apoptosis for cancer cells." (PMID 33807199, 2021). "Additionally, Pin1 promotes the stability and activity of Myc, thereby regulating cell growth and metabolism in cancers." (PMID 33807199, 2021). "Furthermore, we also discuss the multiple roles of Pin1 in cancer hallmarks and examine Pin1 as a desirable pharmaceutical target for cancer therapy." (PMID 33807199, 2021). "Pin1 is widely overexpressed in cancers and plays an important role in tumorigenesis." (PMID 33807199, 2021). "Therefore, Pin1 promotes invasion, metastasis and even other malignant tumor processes partly through the upregulation of β-catenin-mediated signaling cascades." (PMID 33807199, 2021). "In contract to cancer, in AD Pin1 function may be inhibited (by downregulation, phosphorylation, oxidation, or genetic changes), what leads to reduction of isomerization of tau protein and APP." (PMID 34523079, 2021). "However, while the role of Pin1 in proliferating cells and, in particular, in the field of cancer, has been widely characterized, less is known about the functions of Pin1 during the development of the nervous system and in post-mitotic adult neurons." (PMID 33083964, 2021). "Furthermore, proteins that have PPIase activity, such as the Peptidyl-prolyl cis-trans isomerase NIMA-interacting 1 (PIN1), are shown to be upregulated in various cancers and are considered as prognostic markers and as a therapeutic target." (PMID 34830970, 2021). "At present, Pin1 is a desirable pharmaceutical target for cancer therapy, and the present study summarizes the recent progress of Pin1-targeted small-molecule compounds for cancer therapy." (PMID 33807199, 2021). "The dysregulation of Pin1-mediated inflammation contributes to many diseases, including cancer." (PMID 33807199, 2021). "It was demonstrated by Min and co-workers that mice with deletion of Pin1 are resistant to cancer." (PMID 34523079, 2021). "For example, Pin1 inhibitor KPT-6566 may exert anti-cancer effects through at least two simultaneously acting mechanisms: inhibition of Pin1 and ROS production." (PMID 33537091, 2021). "Due to the overexpression of Pin1 in tumor tissues and its role in promoting tumor progression, drugs currently under development for targeting Pin1, including natural products, chemical compounds, and peptide drugs, are mainly focused on cancer treatment." (PMID 33537091, 2021). "Evidence shows that Pin1 could sustain the extending telomeric DNA through destabilizing TRF1 in cancer cells." (PMID 33807199, 2021). "Pin1 is known to promote angiogenesis mainly through the regulation of hypoxia-inducible factor 1α (HIF-1α)-mediated or NF-κB-mediated expression of vascular endothelial growth factor (VEGF) in cancer tissues." (PMID 33807199, 2021). "Furthermore, the other VEGF promoting transcriptional factors, such as β-catenin and FoxM1, are upregulated by Pin1 to drive angiogenesis in various cancers." (PMID 33807199, 2021). "Researches indicated that PIN1 is upregulated in cancer and indicates poor clinical prognosis." (PMID 32703934, 2020). "Furthermore, a recent covalent PIN1 inhibitor, KPT-6566, has shown potency for reducing PIN1-dependent cancer phenotypes." (PMID 32300594, 2020). "However, of all the 17 cancer types analyzed, only in two types, renal and pancreatic, are Pin1 expression prognostic: high Pin1 expression is favorable for better prognosis as determined by Human Protein Atlas." (PMID 32426354, 2020). "In this review, we discuss the roles of PIN1 in cancer and PIN1-targeted small-molecule compounds." (PMID 32258027, 2020). "Upregulated Pin1 controls many Pro-directed phosphorylation signaling events and its modulation is involved in cell cycle coordination, chromosome instability, proliferation, migration, metastasis, and apoptosis in cancer cells." (PMID 32195254, 2020).
cancer (continued). "Additionally, after intervening PIN1 expression, we detected the reported PIN1 targeting genes that related to cancer progression." (PMID 32703934, 2020). "Similarly, inhibiting PIN1 counteracts the cancer-promoting effect of miR-628-5p inhibitor completely." (PMID 32703934, 2020). "This hypothesis is interesting in and of itself, but is inconsistent with the existing literature which suggests other roles of Pin1 in cancer development." (PMID 32426354, 2020). "In summary, we showed that Pin1 may be a marker for the risk of progression to HSIL, and KPT-6566 may be further developed as a cancer therapeutic that inhibits Pin1." (PMID 32010480, 2020). "Mounting evidence has demonstrated that Pin1 is widely overexpressed and/or overactivated in cancer, exerting a critical influence on tumor initiation and progression via regulation of the biological activity, protein degradation, or nucleus-cytoplasmic distribution of its substrates." (PMID 32296699, 2020). "Aberrant Pin1 elevation has been shown to be involved in many signaling events such as cell cycle coordination, chromosome instability, proliferation, migration, metastasis, and apoptosis in cancer." (PMID 32500074, 2020). "PIN1 obviously can be an super attractive target for curing cancer and cancer stem cells." (PMID 32258027, 2020). "Pin1 has been shown to promote cell proliferation and has a protective role against neurodegeneration including AD, however, Pin1 exerts opposite effects on the development of cancer and AD." (PMID 32195254, 2020). "As Pin1 mediates the isomerization of downstream proteins and changes their structures and activities, it has a pivotal role in multiple processes during tumorigenesis and cancer development." (PMID 32347623, 2020). "Peptidyl-prolyl cis-trans isomerase NIMA-interacting 1 (Pin1), an isomerase that specifically recognizes the serine/threonine-proline motif, is overexpressed in several cancers including pancreatic, breast, and prostate and its expression correlates with poor clinical outcomes." (PMID 33322239, 2020). "While Pin1 is highly expressed in the majority of cancers and promotes cancer progression, its expression is down-regulated in neurodegenerative diseases, highlighting the diverse regulatory functions of Pin1 in physiology and diseases." (PMID 32266261, 2020). "Indeed, BJP-06-005-3 is a promising tool for exploring Pin1 biology in human cancer, but its characteristics still need to be improved considering its clinical application in cancer therapy." (PMID 33024085, 2020). "MLK3, a MAP3K family member, phosphorylates Pin1 on a Ser138 site to activate its catalytic function and nuclear translocation, driving the cell cycle and promoting cyclin D1 stability and centrosome amplification of cancer cells." (PMID 32296699, 2020). "Many research have indicated that PIN1 inhibitors suppress different cancers in cell and animal test significantly; however, it is far to apply in clinic treatment for the vital role of PIN1 in normal physiological progresses and the specificity of PIN1 inhibitors." (PMID 32703934, 2020). "Furthermore, the inhibition of PIN1 by PiB treatment destabilizes Nanog, transcription factor required for the essential survival of cancer stem cells." (PMID 32258027, 2020). "Given the fact that global miRNA expression is downregulated in tumors, this reduced miRNA expression could lead to Pin1 overexpression in cancer." (PMID 32296699, 2020). "Accumulated evidence suggests that Pin1 contributes to oncogenesis of diverse cancers." (PMID 32347623, 2020). "Therefore, these achievements provide strong evidence that Pin1 is an attractive target for cancer therapy, leading to the discovery of Pin1 inhibitors for treating cancer and preventing drug resistance." (PMID 32296699, 2020).
cancer (continued). "Pin1 activity and expression are significantly inhibited in human AD brains and highly increased in diverse types of cancers, indicating that Pin1 might have important roles in both proliferation and degeneration." (PMID 32500074, 2020). "In addition, intracellular organelles that regulate the balance between cell survival and death, are also governed by Pin1 in cancer and apoptotic neurons." (PMID 31884567, 2020). "However, Pin1 overexpression contributes to a number of cancers, eliminating the possibility of direct administration." (PMID 32500074, 2020). "In this section, we review the roles of Pin1 in these cancer hallmarks." (PMID 32296699, 2020). "Pin1 participates in the modulation of cancer cell plasticity, shape and migratory abilities." (PMID 32010480, 2020). "Additionally, Pin1 enhances the invasion and metastasis of multiple cancers by activating NF-κB, BRD4, and XPO5." (PMID 32296699, 2020). "PIN1’s contribution to cancer stemness development seems especially significant and multifaceted." (PMID 32268506, 2020). "In cancer stem cells, multiple PIN1 substrates play an important role." (PMID 32258027, 2020). "Moreover, KPT-6566-B, the byproduct of KPT-6566 after Pin1 interaction, produces ROS and increases cancer cell death." (PMID 32195254, 2020). "Additionally, Pin1 participates in cancer development via transcriptional, post-transcriptional, and post-translational mechanisms, and these mechanisms operate in both the nucleus and cytoplasm." (PMID 32296699, 2020). "PIN1 induces the cancer metastasis and invasion by activating β-catenin, BRD4, NF-κB, and p53M." (PMID 32258027, 2020). "Furthermore, Pin1 promotes several hallmarks of cancer through inactivating 26 tumor suppressors and activating 56 oncogenes." (PMID 33322239, 2020). "Additionally, a combination of ATRA and sorafenib for the HCC treatment decreases the expression of PIN1 protein, increases cancer cell death, and represses the HCC growth compared with sorafenib or ATRA alone." (PMID 32258027, 2020). "Pin1 has been reported to enhance the IL‐6/STAT3 pathway in different cancer types." (PMID 32347623, 2020). "In metastatic cancer, PIN1 level is considerably higher than that in primary cancer." (PMID 32258027, 2020). "Thus, Pin1 has both nuclear and cytoplasmic functions, and is extensively involved in the initiation and progression of cancer." (PMID 32296699, 2020). "As discussed, Pin1 can be either pro- or anti-apoptotic depending on the cellular context, and therefore, the role of Pin1 in mitochondria-driven apoptosis could provide a direct mechanical link between cancer and neurodegeneration." (PMID 31884567, 2020). "In most cancers, PIN1 is significantly high expressed and correlates with poor prognosis." (PMID 32703934, 2020). "The overexpression of PIN1 is common in many types of cancer and is correlated with poor outcomes." (PMID 32300594, 2020). "Pin1 is identified as a unique enzyme mediating the cis-trans isomerization of pSer/Thr-Pro motif of proteins specifically, extensively participating in the initiation and progression of many human cancers." (PMID 32296699, 2020). "Selected factors contribute to Pin1 dysregulation in cancer." (PMID 32296699, 2020). "Pin1 has been identified as a positive regulator of p65 in some cancer cells." (PMID 32347623, 2020). "Pin1 is highly expressed in a majority of cancers, and elevation in Pin1 levels by either OSM or IL-6 involves the activation of both STAT3 and NF-κB through direct binding with the pSer/Thr-Pro motifs of STAT3 and p65 in the nucleus that results in promotion of STAT3 transcriptional activation." (PMID 31952344, 2020).